IL6 (interleukin 6)
Diseases named in the same sentence as IL6 in open-access papers (continued):
Sharing a sentence is not in itself a finding about the gene and the disease.
infection (continued). "Other researchers have demonstrated that elevated levels of specific inflammatory markers present during the acute phase of infection—namely, CRP, IL-6, and tumor necrosis factor (TNF)—are correlated with an increased risk of developing long COVID." (PMID 41302639, 2025). "Infections, such as SARS‐CoV‐1, can activate DCs to produce inflammatory cytokines (TNF‐α, IL‐6) and chemokines (MIP‐1α, RANTES, IP‐10, MCP‐1, CCL3, CXCL10)." (PMID 40405557, 2025). "Following infection, macrophages not only directly eliminate fungi by phagocytosis but secrete a series of pro-inflammatory cytokines (e.g., IL-1β, TNF-α, IL-6, and IL-12), biotic factors (e.g., ROS and NO), and enzymes (e.g., lysozyme and acid phosphatase)." (PMID 39949625, 2025). "Monocytes play a critical role in initiating the HIV-1 anti-viral inflammatory response by secreting inflammatory cytokines such as interleukin-6 (IL-6) and tumour necrosis factor-alpha (TNF-α) during the acute inflammatory phase of infection." (PMID 40936922, 2025). "Compared to mice infected with the icmQ::Tn mutant, mice infected with the Ig::Tn strain had approximately 10-fold higher IL-6 levels in sera and PLF at day 3 post-infection." (PMID 40586810, 2025). "K. pneumoniae infection triggered transcriptional upregulation of IL-1β, IL-6, IL-8, and TNF-α within 2 h post-infection, preceding significant changes in ferroptosis markers." (PMID 41343264, 2025). "Specifically, compared with infection at 18°C, GCRV infection at 28°C significantly induces IL-6 expression and STAT3 phosphorylation." (PMID 41488475, 2025). "Infection with L. monocytogenes led to a significant increase in the mRNA levels of IL6, CXCL8, TNF, and IFNG (p < 0.01 for IL6, p < 0.001 for other cytokines), along with a significant decrease in transcription level of IL10 (p < 0.001)." (PMID 41376047, 2025). "In both the B.1.351 model and the AAV-hACE2-WA1 model, intranasal SARS-CoV-2 infection resulted in increases in pro-inflammatory cytokines (e.g., IL-1β, IFNβ, CXCL10, IFNγ, IL-6, and CCL11) in the hippocampus and cerebrospinal fluid at 7 days post-infection." (PMID 39861887, 2025). "Despite the profound lack of interferon induction, Ebola significantly induced inflammatory cytokines, including IL6 and CXCL8/IL8, by 48 hours post-infection." (PMID 41279810, 2025). "QRT-PCR analysis revealed that, relative to the Pm-infected group, the expression levels of IFN-γ, IL-4, IL-6, IL-17, TGF-β, GATA-3, T-bet, RORγt, and FoxP3 genes were significantly elevated in the Pm_OMVs-infected group at 24 hours post-infection (P < 0.01)." (PMID 41306977, 2025). "In pre-infection samples (day 66), animals receiving the combination of live dpB and SARS-CoV-2 vaccination (group 4) showed statistically higher levels of IL-6 and IL-10, than inactivated dpB-SARS-CoV-2 vaccine group (group 2) (M-W, pb< 0.001; M-W, pb=0.040)." (PMID 40969767, 2025). "The immune response to an hMPV infection is characterized by the activation of Th17-like cells, which secrete tumor necrosis factor-alpha TNF-α) and interleukin (IL)-6 in the lungs." (PMID 40176892, 2025). "Nonetheless, elevated IL-1β and TNF-α levels have been reported in the later stages of infection with virulent PRRSV strains, and HP-PRRSV is known to induce systemic cytokine responses, including TNF-α, IFN-α, IL-1, and IL-6, around 7 dpi." (PMID 40630508, 2025). "IFN-β was present at very low levels in mice before infection (pre), while TNF-α, IL-1β, and IL-6 were undetectable." (PMID 40124358, 2025). "The concentrations of IL-6 and IL-8 in culture supernatants were higher following rgDENV2-NS1-K272R infection compared to rgDENV2-NS1-WT at various time points in a time and dose-dependent manner." (PMID 39972477, 2025). "APR is a systemic phenomenon that accompanies inflammation, in which IL-6, interleukin(IL)-1β (IL-1β), and tumour necrosis factor-α (TNF-α) synergistically cooperate to mitigate potential infection and further tissue injury." (PMID 40497942, 2025).
infection (continued). "There was an significantly increase in levels of interleukin 6 (IL-6) and tumor necrosis factor-α (TNF-α) levels after COVID-19 infection, and the cytokine levels decreased as the infection was contained." (PMID 40295300, 2025). "IL-6, IL-1β, and STAT1 expression levels rapidly increased post-infection, peaking at 2 dpi with 11.84-fold, 13.22-fold, and 6.84-fold (all p < 0.05) elevation, respectively." (PMID 41011502, 2025). "In vitro infection models demonstrated that SA reduced TNF-α and IL-6 expression in CHIKV-infected 293T cells and increased the survival rate of infected BHK-21 and 293T cells by ~25%." (PMID 39917312, 2025). "During the later stages of infection, TRIM38 negatively regulates the TLR3/4 signaling, consequently suppressing the production of proinflammatory cytokines including TNF-α, IL-1β, and IL-6." (PMID 40006954, 2025). "Following infection, all neonatal groups mounted significant increases in serum cytokines and chemokines, including G-CSF, GM-CSF, TNF-α, IL-6, MIP-1α, MIP-1β, and RANTES." (PMID 40766470, 2025). "During infection, heightened immune activity elevates pro-inflammatory cytokines such as tumor-necrosis factor-α (TNF-α) and interleukin-6 (IL-6) within the uterine environment." (PMID 40868898, 2025). "We also measured inflammatory cytokine levels (TNF-α, IFN-γ, IL-1β, IL-6, IL-10, and IL-12) in the BALF supernatant 3 days post-infection." (PMID 39655914, 2025). "In the lymph nodes, we observed significant increases in the levels of IL-4, IL-6, TNF, and IFN-γ at 22 days after infection and increases in the levels of IL-2, IL-1, and IL-10 in infected mice at 35 days." (PMID 39899646, 2025). "The abrupt decline in CD73 expression was accompanied by low levels of IL-6 and high levels of IFN-γ in cardiac (14 dpi) and splenic (21 dpi) infection." (PMID 40590226, 2025). "Pa-STING vaccination also significantly reduced levels of IL-1β, IL-6, and TNF-α in the bronchoalveolar lavage (BAL) fluid 20 hours after infection." (PMID 40705476, 2025). "In conclusion, serum TNF-α, IL-6, and IFN-γ levels are significantly elevated in DFI patients, and all three cytokines serve as potential biomarkers for assessing infection severity and prognosis." (PMID 40677522, 2025). "Specifically, LPA levels were negatively correlated with major infection-related and inflammatory biomarkers, such as neutrophil count, PCT, and IL-6 (all P < 0.001)." (PMID 41567194, 2025). "In the acute phase of infection, parasite antigens elicit a robust Th1 response marked by elevated levels of proinflammatory cytokines, including TNF-α, IL-1, and IL-6." (PMID 40365538, 2025). "Infections, especially chronic ones, are characterized by numerous complications resulting from interactions at the cellular level of both TNF-α, IL-6 and IL-8." (PMID 40647668, 2025). "Responses to infection with AIVs in the upper respiratory tract were characterized by upregulation of the IFN-α, IFN-γ, and the IL-6 JAK-STAT pathways." (PMID 40778772, 2025). "Beyond safety concerns, IL-6 inhibition may impair immunological memory: as IL-6 supports B cell maturation, germinal center dynamics, and plasma/memory B cell generation, its blockade can blunt vaccine responses, particularly relevant in SLE populations with elevated infection risk." (PMID 41280899, 2025). "The production of pro-inflammatory cytokines, IL-6, MCP-1, and TNF-α, was substantially elevated at 3 or 7 dpi in the infection control group relative to the treatment groups." (PMID 41165324, 2025). "The up-regulation amplitude was IL-6 > IL-1β > TNF-α, and the up-regulation amplitude increased with extended infection time within 18 h." (PMID 40663568, 2025). "From the perspective of the color scale, the expressions of IL-8, IL-1β, IL-4, IL-6, IL-2, TNF-α, IL-10, and IL-17 showed a significant upward trend as the infection duration increased." (PMID 41165313, 2025).
infection (continued). "Both infection and vaccination from SARS-CoV-2 can induce robust CD4+ T cell responses promoted by an IL-6 amplifier loop of inflammation." (PMID 40552181, 2025). "The high level of IL-6 probably induced IL-10 and VEGF-A expression for possible tissue repair at the initial and late stages of infection." (PMID 40358160, 2025). "In the K18-hACE2-tg mouse model, a cytokine storm including IL-6, IL-17, and IL-4 occurred in the lungs following SARS-CoV-2 Wuhan infection." (PMID 40270072, 2025). "It is recommended to closely monitor immune markers (e.g., IL-6, CRP) during the early stages of infection and to collaborate with specialists in neurology, infectious diseases, and immunology to develop individualized treatment plans." (PMID 40264651, 2025). "IL-1, IL-6, and TNF-α are important pro-inflammatory cytokines released during the early stages of infection." (PMID 41150385, 2025). "Before infection, leukocytes from ITMPRE steers produced more IL-6 (P < 0.01) in response to stimulation with the TLR agonist, Pam3CSK4." (PMID 38853197, 2025). "This response increases cytokine release, particularly IL-6, and promotes ECM-receptor interaction, amplifying immune cell recruitment to sites of infection and enhancing systemic inflammatory responses." (PMID 40136726, 2025). "M1 macrophages are activated during the acute infection phase, releasing cytokines like TNF‐α, IL‐6, and IL‐1β to control infection." (PMID 40060195, 2025). "Pro-inflammatory cytokines, including IL-6 and tumor necrosis factor-alpha (TNF-α), directly enhance PCT expression, a process that can occur independently of infection." (PMID 40963340, 2025). "The levels of proinflammatory cytokines including TNF, IL-1β, IL-6, and MIP-2 were measured in the cell-free supernatants of the P. aeruginosa-infected BMDMs at 3 h post-infection." (PMID 40143103, 2025). "The qPCR experiment showed that the transcription levels of IL-1β, IL-6, and TNF-α in the circ-ZNF277 suppressed THP-1 cells were lower than those in the control THP-1 cells at 0, 12, and 24 h post-infection (p < 0.001)." (PMID 39996735, 2025). "Plasma Interleukin 6 (IL-6) concentrations increased significantly across IDC high, IDC moderate and SIC groups as the infection progressed." (PMID 40407816, 2025). "Prior to infection, animals that had been stimulated with live dpB (group 3) had higher IFN-γ, IL1-β TNF-α and IL-6 values than the group of inactivated dpB stimulated animals (group 1) or the infection controls (that had not been stimulated) (group 5)." (PMID 40969767, 2025). "Under the same infection conditions, Q3G treatment significantly reduced production of IFN-β1, IL-6, and CCL5 (RANTES) in both MR766- and BR15-infected cells." (PMID 40732762, 2025). "Lower pre-infection neutralizing antibodies and RSV-specific IgA; higher airway IL-6/IL-8/MPO in severe cases; CD8+ T cells in BALF protective." (PMID 41583233, 2025). "The levels of IL-6, TNF-α, and MCP-1 at 7 dpi in the doxycycline 25 mg/kg and omadacycline 10 and 15 mg/kg treatment groups were significantly lower than the infection control group." (PMID 41165324, 2025). "The expression of IL-1β and IL-6 in Vero and DF-1 cells is upregulated during early ARV infection, promoting cell migration and infection spread through chemotactic response regulation." (PMID 40059215, 2025). "When we compared the expression of inflammatory cytokine response of adult and pediatric cells upon HMPV and RSV infection, we observed that adult cells produced more pro-inflammatory cytokines (IL-1β, IL-6, IL-8, and TNF-α) following infection." (PMID 40143308, 2025). "The qPCR analysis revealed significant upregulation of IL-6, IL-17A, IL-22, IFN-β, IFN-γ, and TNF-α in duodenal epithelial cells following IBV CSL strain infection." (PMID 40871421, 2025). "Subsequent production of IL-6, IL-12, and CXCL1 by neutrophils recruit additional adaptive cells to the site of infection." (PMID 39966757, 2025).
infection (continued). "Serum levels of TNF-α, IL-6, and IFN-γ were significantly higher in the infection group than in the non-infection group (P<0.05)." (PMID 40677522, 2025). "On day 3 post-infection, cytokine profiling revealed significantly higher levels of IFN-α, IFN-β, TNF-α, CXCL-1, and IL-6 in the lungs of mice infected with the G-extended virus compared to the Δ7AA virus." (PMID 40076707, 2025). "IL-6, TNF-α, IL-10 and other cytokines are important participating factors in the infection related cytokine storm." (PMID 40538651, 2025). "In this study, we observed significant upregulation of IL-6, IL-8, and TNF-α mRNA levels, confirming the successful establishment of a GPS infection model in 3D4/21 cells." (PMID 40636259, 2025). "The secretion of IL-1β, IL-6, and TNF-α was detected using ELISA, while the intracellular survival of Mtb was assessed by CFU counting 24 h post-infection." (PMID 39996735, 2025). "A larger overlap in DEGs was noted between the two time points in the infection group with 74 DEGs that enriched to processes involved in wound repair (HBEGF and MT2A) as well as immune responses to pathogens (CCL20, IL6, and SLAMF1)." (PMID 40576342, 2025). "The capacity of early and mature retinal organoids to respond to T. gondii tachyzoite infection was determined by RT-qPCR for human cytokine transcripts CCL2, CXCL8, CXCL10, and interleukin-6 (IL6)." (PMID 40137771, 2025). "SSO pre-treatment reduced the production of inflammatory cytokines IL-6 and TNF-α on day 3 post-infection, with the lowest levels observed in the group that received intranasal SSO 6 h prior to infection." (PMID 40137298, 2025). "We found that treatment with 5 mg/mL CNF significantly reduced the initial infection rate and significantly decreased the levels of cytokines (IL-β, TNF-α, and IL-6) in the host serum 12 and 24 h after infection (all P < 0.05)." (PMID 40270824, 2025). "Our results showed that baicalin reduced the expression of the pro-inflammatory cytokines tumor necrosis factor alpha (TNF-α), interleukin-1 beta (IL-1β), and interleukin-6 (IL-6) in PPMCs and the peritoneum of piglets after GPS infection." (PMID 40867785, 2025). "A significant increase in IL-6 levels was detected in M.tb-infected, DEM-treated mice at 2 weeks post-infection." (PMID 40001899, 2025). "Beyond mitochondrial DNA, L. infantum-infected neutrophils presented a peak of cytokines gene expressionas IL6 and TNFA 4 h after infection,indicating that these molecules can have an important part in immunecell communication during an infectious process." (PMID 39887021, 2025). "In this study, after the cellular antioxidant system wasinactivated (6 to 8 h post-infection), the inflammatory cytokines mRNA IL-1β, IL-6, IL-8, and TNF-α further increased and reached the maximum value 8 h post-infection." (PMID 41343264, 2025). "ELISA results indicated that the cytokine levels of IL-1β, IL-6, and TNF-α in the serum of mice remained relatively stable at 6 h post-infection." (PMID 40170927, 2025). "Numerical correlations observed for pre-infection cytokines measured in plasma (IL-1β, TNF-α, IL-6, IL-10, IFN-γ and TGF-β) and viral loads in brain, lungs and heart for animals from all the groups of the experiment." (PMID 40969767, 2025). "The inhibitor MI-1851 suppressed the increase in IL-6 levels in EHEC- (p < 0.01) and S. flexneri-mediated infections (p < 0.001)." (PMID 40426498, 2025). "Our results indicated that infection induced the expression of proinflammatory mediators IFN-γ, CCL5, CXCL1, and IL-6 only in the brain." (PMID 39907280, 2025). "For TNF-α, the difference was more significant at 3 h post-infection, while for IL-6 and CXC1/KC, the difference was more significant at 24 h post-infection." (PMID 40818988, 2025).
infection (continued). "These included interferons (IFN-α, IFN-β, and IFN-γ), proinflammatory factors (IL-1β, IL-6, and TNF-α), the anti-inflammatory cytokine (IL-10), and matrix metalloproteinases 3 (which contribute to blood-brain barrier disruption) after TMUV infection." (PMID 40401981, 2025). "Secondarily, the incremental predictive performance of IL-6, CRP, white blood cell count (WBC) and procalcitonin (PCT) to a core model for predicting infection was evaluated." (PMID 40549692, 2025). "Reevaluation of infection markers revealed a progressive increase in C-reactive protein (CRP) and interleukin-6 (IL-6), along with a gradual decrease in platelet count (PLT)." (PMID 40547132, 2025). "Serological analysis revealed a progressive increase in TNF-α, IL-6, and IFN-γ levels with increasing infection severity, with statistically significant differences among the groups (P<0.05)." (PMID 40677522, 2025). "The IL-6/STAT3 signaling pathway, activated by infection and other stimuli, can stimulate T and B lymphocyte proliferation and differentiation, promote synthesis of acute-phase response proteins, and trigger a cascade of inflammatory responses." (PMID 41137299, 2025). "Following infection, female mice exhibited significant increases in the proinflammatory genes IL1B, IL6, and TNFA." (PMID 40143355, 2025). "Infection-induced upregulation of CCL5, IL-6, and IL-8 and increased activation of co-cultured endothelial cells, confirming data collected from cell lines and cord blood-derived mast cells." (PMID 38793609, 2024). "At the early stage of anti‐infection (T1), majority of patients (91.30%, 21/23) in the IAE group showed decreased IL‐6 level compared with the baseline concentration (p = 0.002)." (PMID 38967137, 2024). "At 24 h post-infection, both berbamine and tetrandrine significantly reduced TNF-α, IL-1β, and IL-6 levels compared to the ASFV control by around 60–80%." (PMID 38664855, 2024). "We observed a decrease in IL-1β, IL-6, TNF, and IFNβ levels in the supernatants of GSDMD knockdown (KD) macrophages despite comparable levels of infection as indicated by viral nucleoprotein levels in Western blots." (PMID 38553499, 2024). "In p62 KO HeLa cells, a significant increase in the amount of secreted IL-6 and IL-8 was detected at 4h, 10h and 24h after LF82 infection at a MOI of 10 compared to control cells." (PMID 38606299, 2024). "We found that TNF-α, IL-β, CXCL2, TLR4, and IL-6 (mRNA) and selected proteins (TNF-α, IL-1β, and CXCL2) were upregulated significantly by exposure to the particulate and infection." (PMID 38928968, 2024). "Upon infection with SARS-CoV-2, the human immune system can become overactivated, releasing large amounts of cytokines, such as tumor necrosis factor-α (TNF-α) and IL-6, triggering an excessive inflammatory response." (PMID 39717543, 2024). "When administered after the onset of infection and again 24 h later, MFX effectively reduces cytokine levels—including IL-1β, TNF-α and IL-6—as well as organ lesion markers, such as LDH, ALT and urea." (PMID 39200042, 2024). "There has been extensive work using cell lines and mast cells derived from human cord blood that has shown FcγRII-dependent enhancement of infection, upregulation of CCL3, CCL4, CCL5, IL-1β, and IL-6, and TNF-α-mediated endothelial activation." (PMID 38793609, 2024). "Our first observation indicated that the presence As during the 6 h infection of S. aureus infection of MAC-T cells led to a dose dependent and significant reduction in IL6, IL1β, IL8 and TNFα produced by the infected cells." (PMID 38414081, 2024). "PCT level > 1.39 ng/mL (odds ratio [OR]: 4.23, 95% confidence interval [CI]: 1.15–15.63) and IL-6 level > 84.00 pg/mL (OR: 21.81, 95% CI: 5.68–83.76) on POD 3 were independent predictors of postoperative infection in LGC." (PMID 38504206, 2024).